CDKN2A (cyclin dependent kinase inhibitor 2A)
Diseases named in the same sentence as CDKN2A in open-access papers (continued):
Sharing a sentence is not in itself a finding about the gene and the disease.
pancreatic cancer (continued). "ctDNA analysis of CDKN2A for pancreatic cancer is limited, though one study identified mutations from DNA in pancreatic juice at an incidence of 6% in PDAC and 0% in control cases." (PMID 31608239, 2019). "Cyclin-dependent kinase Inhibitor 2A (CDKN2A) is mutated or its promoter methylated in 95% of pancreatic tumors." (PMID 29382159, 2018). "It was reported that a higher proportion of mutations occurred in CDKN2A in sample probands with familial pancreatic cancer." (PMID 30280037, 2018). "CDKN2A mutation carriers are also at increased risk of the development of pancreatic cancer compared with the general population." (PMID 29774366, 2018). "We therefore stably expressed MTAP in MTAP-deficient pancreatic cancer MIA PaCa-2 cells that contain a homozygous deletion of the CDKN2A locus." (PMID 29983885, 2018). "Since only about 10% of pancreatic cancers are part of all familial cancers, the results showing substantially high mutation rates suggested that detected CDKN2A mutations are prevalent in the region where analysis was performed." (PMID 28452926, 2017). "Inherited modifications in CDKN2A cause familial atypical multiple mole melanoma and an increased risk of pancreatic cancer." (PMID 28452926, 2017). "In an Italian study, there was a strong correlation between familial pancreatic cancer and the CDKN2A mutation, as 5 out of 16 patients (31%) with FPC carried the mutation (225 patients with PDAC enrolled)." (PMID 29069866, 2017). "The study included 178 CDKN2A mutation carriers, 214 individuals with familial pancreatic cancer, and 19 BRCA1/2 or PALB2 mutation carriers." (PMID 29069866, 2017). "In another study, 5/120 (4%) of pancreatic cancer patients had CDKN2A mutations, namely G101W, E27X, and L65P." (PMID 28452926, 2017). "Mutations in the cell cycle regulator p16/CDKN2A are also associated with familiar pancreatic cancer as are mutations in the serine/threonine kinase STK11/LKB1." (PMID 26840568, 2016). "Loss of the cyclin-dependent kinase inhibitor 2A (CDKN2A) tumor suppressor gene function by mutation or promoter methylation is found in 95% of pancreatic tumors." (PMID 27096871, 2016). "One of the most important non-genetic risk factors for developing pancreatic cancer is tobacco use, and even in CDKN2A germline mutation carriers it increases the risk for pancreatic cancer significantly." (PMID 26111702, 2015). "In this study, we systematically reviewed the association between CDKN2A promoter methylation and pancreatic cancer using meta-analysis methods." (PMID 26338139, 2015). "Other genetic variants should thus be considered when studying the risk of pancreatic cancer in CDKN2A mutation carriers." (PMID 26111702, 2015). "Cigarette smoking has been considered to increase the risk of pancreatic cancer;31 therefore, we evaluated the relationship between methylation of CDKN2A and smoking status, in another word, the changes in frequency of CDKN2A alterations by smoking status." (PMID 26338139, 2015). "In a subset of families with CDKN2A mutations, an increased risk of pancreatic cancer has been reported." (PMID 25803691, 2015). "In this case–control study, we analysed seven pancreatic cancer-associated SNPs in a distinctively homogeneous cohort of 185 CDKN2A germline mutation carriers." (PMID 26111702, 2015). "The results of our study strongly suggest that CDKN2A methylation is correlated with an increased risk of pancreatic cancer." (PMID 26338139, 2015). "The results strongly suggest that CDKN2A methylation is correlated with an increased risk of pancreatic cancer." (PMID 26338139, 2015). "The p16/CDKN2A gene is located on the short arm of chromosome 9, and almost all pancreatic carcinomas present a loss of the p16/CDKN2A function." (PMID 24783207, 2014). "Mutations in KRAS and CDKN2A genes in pancreatic cancer are well documented; however, their influence on disease outcome in patients with exocrine pancreatic tumors has remained unclear." (PMID 23565280, 2013).
pancreatic cancer (continued). "In the literature, the presence of pancreatic cancer in MM prone families has been consistently associated with an increased frequency of CDKN2A mutations." (PMID 23653675, 2013). "The other gene that has been consistently reported to carry high frequency of somatic mutation in pancreatic cancers is CDKN2A." (PMID 23565280, 2013). "Virtually all pancreatic carcinomas have loss of P16INK4A/CDKN2A function; in 40% of pancreatic cancer cases there is a homozygous deletion." (PMID 24084722, 2013). "This becomes of extreme importance when a cancer-causing germline mutation has been identified in a family, such as the CDKN2A mutation in the familial atypical multiple mole melanoma-pancreatic cancer (FAMMM-PC) prone syndrome." (PMID 24281205, 2010). "Research on ‘patient friendly’ ways for early diagnosis of pancreatic carcinoma (e.g., detection of tumour associated markers in serum or stool) is badly needed for surveillance of CDKN2A positive families." (PMID 24281082, 2010). "Pancreatic carcinoma appears to be part of the tumor spectrum associated with several CDKN2A mutations worldwide." (PMID 24281082, 2010). "Families with the CDKN2A mutation have an increased risk not only of multiple melanomas and pancreatic carcinoma but also of breast cancer." (PMID 17254323, 2007). "Genetic syndromes, such as those resulting from inherited mutations in genes like STK11, BRCA1, BRCA2, PALB2, CDKN2A, and DNA repair genes, notably elevate the risk of pancreatic cancer, particularly in individuals with a family history of pancreatic cancer among first-degree relatives." (PMID 39949443, 2025). "In 46%–60% of pancreatic cancers, inactivating mutations of CDKN2A have been detected." (PMID 40264765, 2025). "The lifetime risk of pancreatic cancer in CDKN2A pathogenic variant carriers is high (17–21% at 70–75 years of age), however with this incidence, segregation assays may result in false negative even in prospectively followed cohorts." (PMID 38961426, 2024). "Thus, APC alterations were highly associated with colorectal cancer; KRAS alterations and normal APC were highly associated with pancreatic cancer; and CDKN2A alterations and normal APC and KRAS were highly associated with biliary tract cancer." (PMID 38672586, 2024). "CDKN2A mutations and methylation play a crucial role in pancreatic cancer pathogenesis." (PMID 38666907, 2024). "The association with a higher risk of developing pancreatic cancer is evident, and families with CDKN2A germline mutations may exhibit a pancreatic cancer-melanoma syndrome." (PMID 38666907, 2024). "Overall, there is therapeutic potential in inhibiting the progression of pancreatic cancer by targeting CDKN2A mutations, but further research is essential to fully comprehend the effectiveness of these treatments and develop more precise and impactful therapeutic strategies." (PMID 38666907, 2024). "Head and neck squamous cell carcinoma has a loss rate of CDKN2A that may exceed 80%, and esophageal cancer, ovarian cancer, and pancreatic cancer all show evidence of homozygous loss of CDKN2A." (PMID 38206516, 2024).
pancreatic cancer (continued). "On the other hand, germline mutations in BRCA2 or CDKN2A have been suggested as explanations for the link between MM and breast cancer, and CDKN2A mutations have also been proposed as a cause of the increased risk of pancreatic cancer." (PMID 37297018, 2023). "CDKN2A mutations occur in 30–50% of pancreatic cancer cases." (PMID 37460806, 2023). "Additionally, germline mutations in CDKN2A encoding the tumour suppressor p16 are associated with a 17% increased risk of developing pancreatic cancer." (PMID 36500723, 2022). "In addition, PVs in the CDKN2A gene also increase risk for pancreatic cancer (~5–24% lifetime risk)." (PMID 35372037, 2022). "We identified the CDKN2A(47T>G)/p16-L16R variant in four multigeneration kindreds of Mayo Clinic patients that contained members diagnosed with familial pancreatic cancer and melanoma." (PMID 33823155, 2021). "CDKN2A mutations are observed in 5–35% of all pancreatic cancer cases." (PMID 34064761, 2021). "In pancreatic cancer, the early onset risk could be due to high risk genes such as CDKN2A, BRCA1, and BRCA2, or some known rare genes, while the second peak at age 40–49 matches the age of onset of Lynch syndrome." (PMID 34503195, 2021). "KRAS mutation and CDKN2A deletion are occurred in the initiating stage of pancreatic cancer." (PMID 32950968, 2020). "Germline pathogenic variants in CDKN2A/ARF have been found in 20–45% of familial CM cases and in 11–19% of multiple primary melanomas (MPM) from the Italian population, characterized by a high prevalence of CDKN2A pathogenetic variants often associated with pancreatic cancer (PC) and other cancers." (PMID 32325837, 2020). "Interestingly, in a subset of pancreatic cancers retaining CDKN2A, somatic mutations of other cell-cycle regulators such as FBXW7 or ANAPC2 occur." (PMID 29156578, 2017). "It should be mentioned that among the major categories of human tumors, the highest rate of CDKN2A mutations has been found in pancreatic cancer, and that the mutational spectrum of pancreatic cancer is comparable to the overall spectrum of mutations in CUP detected by us and others." (PMID 27322425, 2016). "Finally, carriers of a CDKN2A mutation have an increased risk for different tumors, with pancreatic cancer being the most frequently reported, and more recently, smoking-related tumors." (PMID 25874698, 2015). "Among 15 families with pancreatic cancer and CM, we found 1 family with a CDKN2A mutation." (PMID 25803691, 2015). "In addition to homozygous deletions and mutation, frequent 5′-CpG island methylation of CDKN2A gene promoter resulting in transcriptional silencing of this gene is noted as an important event in the development of pancreatic cancer." (PMID 26338139, 2015). "In the 13 families with CDKN2A mutations, only 1 had a case of pancreatic cancer, in a person with unknown carrier status (the same family as above)." (PMID 25803691, 2015). "Alternatively, there may be a genotype-phenotype correlation between the position of mutations in CDKN2A and risk of pancreatic cancer." (PMID 25803691, 2015). "It is unknown if pancreatic cancer among CDKN2A mutations carriers in different geographic regions is caused by life-style factors, environmental factors, or genetic modulators." (PMID 25803691, 2015).
pancreatic cancer (continued). "In addition, CDKN2A methylation was associated with worse survival in pancreatic cancer, HR = 4.46, 95% CI = 1.37–14.53, P = 0.01." (PMID 26338139, 2015). "We found a low frequency of pancreatic cancer in CDKN2A mutation-positive families in Denmark, and only 1 of 15 families (6.7%) with pancreatic cancer and CM had a CDKN2A mutation, in a person with unknown carrier status." (PMID 25803691, 2015). "Because of these encouraging results from previous studies, it can be expected that genetic variants could also be identified in CDKN2A mutation carriers which influence pancreatic cancer risk." (PMID 26111702, 2015). "Although germline and sporadic mutations have been identified with carriers of the germline p16-Leiden mutation, having an estimated 17% risk of developing pancreatic cancer by the age of 75, CDKN2A has been identified as one of the most frequently inactivated somatic tumor suppressors in PDAC." (PMID 24624093, 2014). "Furthermore, the association of CDKN2A (MIM:600160) with pancreatic cancer had been curated in OMIM." (PMID 24498199, 2014). "Pancreatic cancer is characterised by several key genetic alterations such as activating mutations in the KRAS oncogene or inactivation in the CDKN2A/INK4A tumour suppressor gene that result in abnormal cell signalling and altered control of cell proliferation." (PMID 20664591, 2010). "CDKN2A is mutated in about 10–15% of samples, with the highest incidence in pancreas tumours." (PMID 19402918, 2009). "In addition, the patient's uncle died of pancreatic cancer, a cancer that had been associated with CDKN2A germline mutations, and three other family members died of cancer, but no clinical details were reported to the clinician." (PMID 18612309, 2008). "Germline truncating mutations in CDKN2A, such as E119X and Q50X, have recently been identified in patients with familial “pancreatic cancer plus melanoma syndrome”, a rare cancer predisposition syndrome associated with increased risk of pancreatic cancer and malignant melanoma." (PMID 41228342, 2025). "Moreover, it is indicated that CDKN2A might also drive the pancreatic cancer initiation and progression, because somatic mutations of CDKN2A are widespread in about 95% of pancreatic cancer patients." (PMID 36961395, 2023). "Furthermore, CDKN2A hypermethylation may be a risk factor for a poor prognosis of pancreatic cancer." (PMID 36186479, 2022). "However, research has revealed that germ line mutation of CDKN2A could lead to familial pancreatic cancer with low prevalence in populations." (PMID 35154607, 2021). "The investigated chr9:g.21971058C>A (hg38) founder mutation is the most frequently observed missense CDKN2A variant in familial melanoma cancers with hints that the specific mutation might confer a higher risk of developing pancreatic cancer than other pathogenic CDKN2A variants." (PMID 34680288, 2021). "In conclusion, we observed a novel association in a pleiotropic region that has been found to be of key relevance in the susceptibility to various types of cancer and diabetes suggesting that the CDKN2A/B locus could represent a genetic link between diabetes and pancreatic cancer risk." (PMID 27486979, 2016). "For example, a PB screen identified recurrent transposon insertions in a 200-kb noncoding region (Ncruc) upstream of the Cdkn2a gene, which encodes the tumor suppressors p16Ink4a and p19Arf and is frequently inactivated by prototypic gene-body insertions in both SB and PB pancreatic cancer screens." (PMID 26481584, 2015).
pancreatic cancer (continued). "Here, we demonstrated that combining KRAS inhibitors with gemcitabine effectively overcomes the resistance phenotype associated with CDKN2A loss, highlighting a potential therapeutic strategy for this resistant subset of KRAS-mutant pancreatic cancer." (PMID 40382842, 2025). "The AGA recommends initiating surveillance for pancreatic cancer in patients with a PRSS1 mutation and a CDKN2A mutation at the age of 40 years, which is similar to that by CAPS and the ASGE." (PMID 39200847, 2024). "The synergistic effect was also observed in the MTAP‐deleted (CDKN2A‐deleted) pancreatic cancer cell line KP4." (PMID 39309689, 2024). "The tumor suppressor gene CDKN2A is commonly inactivated in pancreatic cancer and can be detected as early as PanIN-2 lesions." (PMID 39001551, 2024). "In familial pancreatic cancer (FPC), CDKN2A mutations, along with those in BRCA2 and PALB2, were prevalent, particularly in FPC probands, highlighting their significance in hereditary pancreatic cancer." (PMID 38666907, 2024).